RNF217 (ring finger protein 217)
Description:
E3 ubiquitin-protein ligase which accepts ubiquitin from E2 ubiquitin-conjugating enzymes in the form of a thioester and then directly transfers the ubiquitin to targeted substrates. Mediates the degradation of the iron exporter ferroportin/SLC40A1 and thus regulates iron homeostasis.
Synonyms: C6orf172; IBRDC1; OSTL; MGC26996; dJ84N20.1
Tractability: Antibody: UniProt predicts a signal peptide or a membrane-spanning region. PROTAC: ubiquitination databases record sites on it.
Gene: Protein-coding gene on chromosome 6 (124,962,437 to 125,092,633, forward strand). Ensembl gene ENSG00000146373.
Subcellular location: Membrane; Cytoplasm
Pathways (Reactome):
Immune System: Antigen processing: Ubiquitination & Proteasome degradation
Gene Ontology:
Molecular function: ubiquitin conjugating enzyme binding; ubiquitin protein ligase activity; ubiquitin-protein transferase activity; zinc ion binding
Biological process: ubiquitin-dependent protein catabolic process; protein ubiquitination
Cellular component: cytoplasm; cytosol; ubiquitin ligase complex; membrane
Genetic constraint (gnomAD): Loss-of-function variants: 28 observed, 48.42 expected, observed/expected ratio (o/e) 0.58, 90% interval 0.43 to 0.79. The upper end of that interval is the gene's LOEUF score, 0.79, which puts it in group 3 of 6, group 1 being the genes least tolerant of losing a copy. Missense variants: 637 observed, 643.07 expected, observed/expected ratio (o/e) 0.99, 90% interval 0.93 to 1.06. Synonymous variants: 286 observed, 269.43 expected, observed/expected ratio (o/e) 1.06, 90% interval 0.96 to 1.17.
Homologues: Orthologues: chimpanzee RNF217 (99% identical), macaque RNF217 (95% identical), pig RNF217 (89% identical), rat Rnf217 (80% identical), mouse Rnf217 (79% identical), dog RNF217 (73% identical), zebrafish rnf217 (42% identical), tropical clawed frog rnf217 (33% identical), Caenorhabditis elegans C17H11.6 (13% identical), Caenorhabditis elegans Y49F6B.9 (11% identical). Paralogues in human: ANKIB1 (16% identical), ARIH1 (14% identical), RNF14 (13% identical), RNF19A (13% identical), RNF19B (13% identical), ARIH2 (12% identical), RNF144B (12% identical), PRKN (11% identical), RNF144A (11% identical).
Diseases named in the same sentence as RNF217 in open-access papers:
RNF217 is named in the same sentence as 7 diseases in open-access papers, as found by Europe PMC text mining. Sharing a sentence is not in itself a finding about the gene and the disease. The quoted sentences say what the papers report.
alcohol (1 paper, 2022). "In the choline supplemented model, significant hypermethylation of RNF217 was found, which has also been seen with alcohol-related HCC in humans." (PMID 36474183, 2022).
leukemia (1 paper, 2022). A malignant (clonal) hematologic disorder, involving hematopoietic stem cells and characterized by the presence of primitive or atypical myeloid or lymphoid cells in the bone marrow and the blood. "The RNF217 protein is a member of RING1-IBR-RING24 (RBR) ubiquitin protein ligase family, which contains a transmembrane domain and regulates apoptosis signaling by interacting with HAX1 to promote leukemia development." (PMID 35654793, 2022).
neuroblastoma (1 paper, 2019). Neuroblastoma (NB) is the most common solid, extracranial childhood tumor. "The other RNAs considerably over-expressed in MYCN-amplified neuroblastoma cell lines were RP11-102F4.3, RNF217, GRIK3, and SLCO5A1." (PMID 31690716, 2019). "Here our RNA sequencing analysis identifies N-Myc, MYCNOS, IGF2BP1, lncNB1, RNF217, RP11-102F4.3, GRIK3, and SLCO5A1 as the RNAs most considerably over-expressed in MYCN-amplified, compared with MYCN-non-amplified, neuroblastoma cell lines." (PMID 31690716, 2019).
polyneuropathy (1 paper, 2022). A disease or disorder affecting more than one nerve. "Rare variants in RNF217 are associated with polyneuropathy, and rs73580047 (p.R457H) detected in FMS05 has a P value of 0.08 and a beta of 0.6 for this condition in Genebass." (PMID 36216875, 2022).
cancer (2 papers, 2019 to 2022). A tumor composed of atypical neoplastic, often pleomorphic cells that invade other tissues. "The 3′-UTR piSNVs in gene RNF217 occurred in 63 patients across 10 cancer types." (PMID 35654793, 2022). "Again genes involved in other cancer-relevant processes such as cell proliferation, migration, differentiation, apoptosis, or cytoskeletal remodeling were among the driver candidates (all underexpressed with reduced copy number: ARHGAP18, DUSP10, PAK7, PDGFC, RNF217)." (PMID 31682594, 2019).
RNF217 also shares sentences with these, for which no sentence is quoted: lung carcinoma (1 paper); tumours (1).